RETN (resistin)
Diseases named in the same sentence as RETN in open-access papers (continued):
Sharing a sentence is not in itself a finding about the gene and the disease.
Obesity (continued). "High concentrations of resistin caused by genetic or external factors, such as obesity and diet, can play an important role in the pathogenesis of some neoplasms, such as breast cancer." (PMID 32903534, 2020). "The expression of adipokines including leptin, adiponectin, and resistin is dysregulated in obesity and closely associated with secondary metabolic diseases." (PMID 32586265, 2020). "High concentrations of resistin caused by genetic or external factors, such as obesity and diet, can play an important role in the pathogenesis of some neoplasms, such as breast cancer, for example." (PMID 32903534, 2020). "In a recent meta-analysis study, increased plasma resistin level has been linked to an enhanced incidence of obesity-related cancers, such as breast, endometrial, and colorectal cancer, although resistin level cannot be considered a predictor factor." (PMID 32660156, 2020). "Despite associations between resistin and obesity or insulin resistance in animal models, its role in human disease is not clear." (PMID 31690939, 2020). "In this regard, resistin was originally identified as a molecule with the ability to mediate insulin resistance in mice and insulin resistance in obesity is a well-recognized cause of cardiac hypertrophy and dysfunction." (PMID 32000666, 2020). "Further, depletion of resistin in leptin-deficient (ob/ob) and diet-induced obesity mice improved hepatic glucose production and increased peripheral glucose uptake." (PMID 31208019, 2019). "Data from rodent models revealed an association between resistin and the presence of metabolic diseases including obesity and type 2 diabetes." (PMID 31569348, 2019). "It was shown that resistin is linked to several inflammatory disorders including obesity, type 2 diabetes, cardiovascular disease, and asthma." (PMID 31236417, 2019). "Resistin is an adipocyte-derived polypeptide which have been associated with obesity, insulin resistance (IR) and cardiovascular risk." (PMID 31416473, 2019). "This review highlights molecular mechanisms underlying obesity associated hypothalamic inflammation and insulin resistance with particular focus on the role of resistin/TLR4 signaling pathway." (PMID 30906281, 2019). "Beside its role in obesity and insulin resistance, resistin is greatly implicated in proinflammatory processes which are causally involved in the development of insulin resistance in both rodents and humans." (PMID 30906281, 2019). "Murine resistin is mainly implicated in the pathogenesis of obesity-mediated insulin resistance and type 2 diabetes, but the concrete target cells remain inconclusive." (PMID 30809105, 2019). "Single nucleotide polymorphisms (SNPs) in RETN are linked to obesity and insulin resistance in various populations." (PMID 31236417, 2019). "It is also remarkable that the excess of resistin is among the cytokines that define the metabolic unhealthy state, associated with obesity, as demonstrated by the decrease of circulating resistin levels after bariatric surgery." (PMID 31694146, 2019). "In recent years, interest has grown about some novel adipokines, chemerin, visfatin, resistin and apelin, which have been found to be strongly associated with obesity and insulin-resistance." (PMID 31505789, 2019). "Research on the role of resistin in human disease associated with obesity has been challenging due to differences between mouse and human resistin in homology and cellular sources." (PMID 30915034, 2019). "In this review, we present an overview of the molecular mechanisms underlying obesity-induced hypothalamic inflammation and insulin resistance with peculiar focus on the role of resistin/TLR4 signaling pathway." (PMID 30906281, 2019). "The adiponectin–resistin ratio has been suggested by various researchers to be an indicator of metabolic risk for obesity." (PMID 31195622, 2019).
Obesity (continued). "Both adiopkine resistin and ER stress are proposed to be associated with insulin resistance and CVDs in obesity and type II diabetic mellitus." (PMID 30416448, 2018). "The adipose tissue-derived adipokines such as adiponectin, leptin, visfatin, resistin and adipsin are associated with obesity and obesity-related metabolic disorders including T2DM." (PMID 29785210, 2018). "DNAJC27 was found to be associated with leptin and resistin, adipokines known to be dysregulated in obesity, that stimulate inflammatory processes leading to metabolic disorders." (PMID 30131766, 2018). "To conclude, this study investigates the role of increased levels of obesity-associated important adipokines leptin and resistin in melanoma growth and the outcome of DTIC-based therapy." (PMID 29568521, 2018). "In turn, the proinflammatory cytokines including IL-6 and TNF-α can be promoted by resistin, thus decreasing obesity-associated inflammation." (PMID 30050954, 2018). "A strong association was also observed between DNAJC27 level and resistin, another adipokine implicated in the etiology of obesity." (PMID 30131766, 2018). "For instance, adipokines, such as leptin, TNF-alpha and resistin, have a pro-inflammatory role and are associated with an increased risk of obesity comorbidities such as T2D and cardiovascular diseases." (PMID 30451909, 2018). "Previous studies have reported that resistin is associated with obesity, visceral fat, and the etiology of DM22,23." (PMID 30228288, 2018). "As observed in our previous study, by controlling obesity, tumor growth is restricted partly through normalization in the serum levels of obesity-associated factors such as leptin and resistin." (PMID 29568521, 2018). "Obesity-associated factors or adipokines, especially leptin and resistin, are purported to promote growth, survival, proliferation, and invasiveness of cancer cells." (PMID 29568521, 2018). "Further, to complement the role of leptin and resistin and other obesity-associated factors in cell growth, long-term cell survival assay was performed." (PMID 29568521, 2018). "The correlation between obesity and resistin was supported by the findings of studies concerning obesity management, whereby weight loss by diet and exercise or bariatric surgery led to a reduction in resistin in parallel with BMI reduction." (PMID 29138754, 2017). "Previous studies have shown that circulating resistin levels are correlated with risk factor of MS such as type 2 diabetes mellitus, obesity, and rheumatoid arthritis." (PMID 29258500, 2017). "Subsequently, the adiponectin–resistin (AR) index, proposed as an indicator of the metabolic risk in obesity, was significantly higher in serum of obese individuals, especially in these with MS, which again is consistent with previous findings." (PMID 29213336, 2017). "In humans, elevated circulating resistin levels are significantly related to increased risk of type 2 diabetes, while resistin has been implicated in the pathogenesis of obesity-mediated insulin resistance and type 2 diabetes in rodent models." (PMID 28490838, 2017). "This study reflects that the increase in resistin is associated with obesity, which is a predisposing factor for type 2 diabetes mellitus." (PMID 29138754, 2017). "The adipocytes-derived hormone resistin is postulated to be linked to obesity, insulin resistance and diabetes." (PMID 28953247, 2017). "In this study, high salivary resistin was associated with obesity, which is a major predisposing factor for type 2 diabetes and also a risk factor for oral diseases." (PMID 29138754, 2017). "Several studies have also associated the RETN rs1862513 polymorphism with obesity, insulin sensitivity, type 2 diabetes, and cerebrovascular disease." (PMID 29386698, 2017). "In this study, salivary resistin was correlated with obesity which is a predisposing factor for type 2 diabetes." (PMID 29138754, 2017).
Obesity (continued). "The results of studies concerning the possible links between resistin and obesity are rather disputable, but some reports demonstrated reduced resistin levels following the loss of body weight in humans." (PMID 29142618, 2017). "Keeping in mind the role of resistin in linking obesity to colorectal cancer risk, as well as the inconsistent published results regarding the effect of resistin in this setting, this meta-analysis is of special importance." (PMID 27642602, 2016). "We propose that lycopene of tomato extract reduces oxidative stress due to inflammation associated with obesity and consequently reduces resistin and other associated adipocyte production." (PMID 27430475, 2016). "Macrophages are the main source of resistin and obesity causes a significant macrophage infiltration of visceral white adipose tissue." (PMID 28097156, 2016). "Our findings indicated high resistin levels were associated with increased obesity-related cancer risk." (PMID 27509174, 2016). "Among cytokines associated with obesity, circulating leptin and resistin levels were reduced in BP3KO mice compared with wild-type mice on HFD, while MCP-1 levels were similar between chow and HFD groups but were significantly lower in BP3KO than WT." (PMID 27448965, 2016). "The results of our meta-analysis suggested circulating resistin levels were higher in obesity-related cancer patients and an independent risk factor of obesity-related cancers." (PMID 27509174, 2016). "Though associated with obesity and diabetes in population studies, resistin is thought to be secreted from infiltrated macrophages rather than adipose tissue itself." (PMID 27637079, 2016). "We found captured, MVAs expressed significantly higher levels of TNFA, CEBPA, and KLF2 transcripts than MSA, all of which favor reduced levels of adipogenesis in VAT and higher levels of RETN and SERPINs, which are linked to obesity-related disease risk." (PMID 27462403, 2016). "In rodents, it is primarily produced in adipocytes and influenced by genetic and diet, causing increased release of resistin in mouse models of obesity." (PMID 27637079, 2016). "The present study aimed to evaluate the association of circulating resistin levels with the risk of obesity-related cancers by conducting a meta-analysis." (PMID 27509174, 2016). "Although many studies provided evidence that high resistin levels were associated with the risk of obesity-associated malignancies, some studies observed different results." (PMID 27509174, 2016). "In mice, release of resistin is influenced by both genetics and diet, causing increased serum levels of resistin mouse models of obesity." (PMID 26097512, 2015). "Another study has shown that HFD-induced obesity in rodents is associated with the elevation of serum resistin levels and hepatic insulin resistance." (PMID 25922835, 2015). "In postmenopausal, and in obese women, resistin levels nearly double, representing the hormone that links obesity to diabetes; in addition, a close association of resistin to metabolic syndrome has been recently established." (PMID 25254044, 2014). "Some authors indicated that increased serum resistin levels are associated with increased obesity, visceral fat, insulin resistance, and T2DM, while other groups failed to observe such correlations." (PMID 24741591, 2014). "Adipocytokines such as TNFα, IL-6, adiponectin, leptin, visfatin, and resistin are cytokines secreted primarily by visceral adipose tissue and are thought to be involved in the positive correlation between obesity and the increased risk of gastric cancer." (PMID 24929539, 2014). "Our results suggest that obesity influences cardiovascular risk primarily through changes in leptin and resistin and less efficiently at the level of adiponectin." (PMID 24736687, 2014). "Even though, resistin was associated with obesity and insulin resistance in rodents, human data is conflicting in this regard." (PMID 24716628, 2014).
Obesity (continued). "Resistin, an adipokine that has been linked to the onset of obesity-associated diabetes, was reduced in BB enriched diets." (PMID 25501421, 2014). "Studies have shown that loss of resistin in obesity decreases the blood glucose levels and improves insulin sensitivity." (PMID 23634778, 2013). "The association between resistin, BMI, obesity, markers of insulin resistance, oxidative stress and sleep study characteristics was analysed." (PMID 23497617, 2013). "It has been reported that resistin is involved in the pathogenesis of obesity-associated insulin resistance." (PMID 23825152, 2013). "Although resistin (a marker of adiposity), and adiponectin have been linked to obesity and diabetes, these genes were unaltered by chronic low-moderate prenatal EtOH exposure." (PMID 23533642, 2013). "Resistin is another adipokine that antagonizes insulin action, causing glucose intolerance – resistin-deficient animals are protected from obesity – whereas elevated resistin is associated with insulin resistance." (PMID 23530957, 2013). "Resistin, a gene that is linked to obesity, insulin resistance, and breast cancer, was expressed more than four times higher in AA tumors." (PMID 24324792, 2013). "A large study of over 1000 patients suggested that elevated adiponectin and resistin (another adipokine) were only weakly associated with OA and obesity but there was a stronger positive correlation between OA and obesity and leptin." (PMID 24304704, 2013). "Although it was non-significant in the case of the young men, both the elderly and the young men who are carriers of the minor alleles shared an increase in resistin levels, a hormone which has been related to obesity, or an increase in insulin resistance." (PMID 22916254, 2012). "Circulating levels of resistin are increased in obesity, and an increase in serum resistin level has been shown to induce insulin resistance in rodents, suggesting that hyperresistinaemia has a causal relationship with obesity-associated insulin resistance." (PMID 22762794, 2012). "Current evidence suggests that resistin has been variably associated with obesity, insulin resistance, inflammation, and renal dysfunction." (PMID 22567283, 2012). "Initial findings have been reported regarding an association between obesity and elevated plasma resistin levels." (PMID 21410966, 2011). "Resistin, the adipocytokine initially linked to obesity and insulin resistance in humans, has been shown to be more related to inflammation and has been associated with cardiovascular risk factors, including hypertension." (PMID 21483749, 2011). "Resistin is an adipocytokine that is associated with obesity-mediated insulin resistance and increased cardiovascular risk." (PMID 20706676, 2010). "Hyperresistinemia impairs glucose tolerance and induces hepatic insulin resistance in rodents, whereas mice deficient in resistin are protected from obesity associated insulin resistance." (PMID 19473519, 2009). "Adipocyte enlargement, as observed in obesity, is associated with dysfunctional fat cells which over-express and secrete excessive amounts of leptin, IL-6, TNFα, resistin, MCP-1 and FFA while under secreting adiponectin." (PMID 19656356, 2009). "In animal models resistin is clearly linked to obesity, metabolic syndrome and type 2 diabetes, in which hyperglycemia and hyperinsulinemia increase resistin expression." (PMID 19545363, 2009). "Resistin administration or hyperresistinemia impairs glucose tolerance and induces hepatic insulin resistance, whereas mice deficient in resistin are protected from obesity-associated insulin resistance." (PMID 16854242, 2006). "Because in mice higher resistin levels (produced by fat cells) are linked to diabetes, one possibility is that obesity in humans, by being similar to inflammation, causes immune cells to make lots of resistin and hence promotes diabetes that way." (PMID 15578112, 2004).
Obesity (continued). "Overweight and obesity increased adiposity may enhance a proinflammatory microenvironment through increased production of adipokines such as leptin, visfatin, and resistin, which have been linked to elevated CRP, TNF-α, and IL-6 levels." (PMID 41517610, 2026). "Resistin, another key adipokine associated with obesity, may play a particular role in exacerbating inflammatory states, suggesting a potential link between excess adipose tissue and the etiology of depression." (PMID 40507778, 2025). "Similarly, resistin is elevated in obese individuals but clinical associations with dementia differ depending on age, obesity phenotypes, and comorbidities, reflecting uncertainties around human secretory dynamics." (PMID 41155642, 2025). "In addition to peripheral insulin resistance, obesity impairs insulin sensitivity in the hypothalamus, where the central Resistin/TLR4 signaling axis has been implicated in promoting hypothalamic inflammation and systemic metabolic dysfunction." (PMID 41282294, 2025). "Obesity, particularly abdominal obesity, is strongly associated with HS severity, as visceral adipose tissue secretes pro-inflammatory adipokines like leptin and resistin, which promote Th1 and Th17 polarization." (PMID 39858932, 2025). "Furthermore, the administration of GE significantly reduced the concentrations of leptin and resistin in serum, which are adipokines closely associated with obesity-related metabolic dysfunction." (PMID 41007640, 2025). "Similarly, circulating levels of resistin are frequently elevated in obesity and have been implicated in the pathogenesis of insulin resistance." (PMID 40733199, 2025). "Integrating TMAO and resistin into routine assessments could enhance personalized risk evaluation and aid in developing targeted therapeutic strategies to mitigate obesity-related metabolic and cardiovascular complications." (PMID 40077669, 2025). "In our study obese (BMI ≥ 30 kg/m2) and overweight (BMI 25–29.9 kg/m2) participants had higher resistin level compared to its counterpart, findings that supports the role of resistin as a biochemical adipokine actively involved in and associated with the pathophysiology of obesity." (PMID 41315571, 2025). "One argument is that other adipokines (such as IL-6, TNF-α and leptin) predominate in the inflammatory profile in higher obesity states, and resistin, which is more closely linked to immune cell activation, may not scale up further with additional adiposity." (PMID 41011232, 2025). "Additionally, their high predictive accuracy confirms the usefulness of sdLDL and resistin as biomarkers for early risk assessment and shows how they can guide early intervention strategies for metabolic and cardiovascular risk linked to obesity." (PMID 41315571, 2025). "Obesity may predispose individuals to chronic kidney disease (CKD) directly through the production of adiponectin, leptin, and resistin, as well as its association with the histopathological features of obesity-related glomerulopathy." (PMID 41009007, 2025). "The excess of adipose tissue in obesity is associated with a shift in adipokine secretion towards a pro-atherosclerotic profile, in which the adiponectin level is reduced while resistin and inflammatory cytokines levels will be steadily increased as macrophage recruitment rises." (PMID 39061938, 2024). "Numerous studies showed a possible association of resistin and adiponectin with obesity and PCOS." (PMID 39457645, 2024). "Some studies suggested that women with PCOS may have a specific resistin gene polymorphism linked to the BMI, emphasizing the connection between obesity and PCOS." (PMID 39273337, 2024). "Although resistin was first described as a factor contributing to insulin resistance and diabetes mellitus in humans, it has also been linked to obesity, although its exact role remains unclear." (PMID 39184804, 2024).